ORMDL3 (ORMDL sphingolipid biosynthesis regulator 3)
Diseases named in the same sentence as ORMDL3 in open-access papers (continued):
Sharing a sentence is not in itself a finding about the gene and the disease.
asthma (continued). "In order to define all the distal cis-regulatory elements that potentially regulate ORMDL3 expression in an asthma-risk genotype-dependent manner, we performed 4C-Seq assays in primary CD4+ T cells from subjects homozygous for the risk (n=4) and non-risk alleles (n=4)." (PMID 27848966, 2016). "Further meta-analysis has showed that SNP rs7216389 in the ORMDL3 may play essential and independent predisposing roles in ethnically diverse populations for both childhood and adult-onset asthma." (PMID 27658857, 2016). "Acevedo and colleagues studied the association of childhood asthma with CpG sites polymorphisms, regional DNA methylation and gene expression at the GSDMB/ORMDL3 locus, which is located at 17q21, a novel asthma-susceptibility locus found in ethically diverse populations." (PMID 26668064, 2015). "This suggested that variants at this asthma susceptibility locus may regulate ORMDL3 expression, having also been confirmed in rhinovirus-infected blood cells." (PMID 26637347, 2015). "ORMDL sphingolipid biosynthesis regulator 3 (ORMDL3) is a universally confirmed susceptibility gene for asthma and has recently emerged as a crucial modulator in lipid metabolism, inflammation and endoplasmic reticulum (ER) stress-the mechanisms also closely involved in atherosclerosis (AS)." (PMID 26603569, 2015). "Over 100 genes have been identified in association with asthma; among them, the orosomucoid-like 3 gene (ORMDL3) and the associated 17q21 locus have emerged through genome-wide association studies as likely contributors to the genetic susceptibility and underlying pathogenesis of asthma." (PMID 26637347, 2015). "Orosomucoid-like 3 gene (ORMDL3) and the asthma susceptibility locus 17q21 have been strongly and reproducibly linked to childhood asthma, but how this gene is functionally linked to asthma is incompletely understood." (PMID 26637347, 2015). "In humans, ORMDL3 was reported as genetic risk factor associated to asthma." (PMID 25192280, 2014). "It has been well established by a series of independent genome-wide association studies (GWAS) that ORMDL3 is a risk factor for the development of many immune-related diseases, e.g. asthma, recurrent wheeze, ulcerative colitis, ankylosing spondylitis, type 1 diabetes and rheumatoid arthritis." (PMID 23577138, 2013). "Association of ORMDL3 in both asthma and IBD is of interest because the lung and gut are composed of similar mucosal surface cells and these tissues are exposed to many potentially harmful antigens and allergens requiring tight regulation of the mucosal immune system." (PMID 23369242, 2013). "The first GWAS for asthma was completed involving 994 childhood-onset asthma patients and 1,243 non-asthma controls and identified single nucleotide polymorphisms (SNPs) within chromosome 17q21 spanning the ORMDL3/GSDMB genes." (PMID 24066901, 2013). "Orosomucoid 1-like 3 (ORMDL3) gene was strongly linked with the development of asthma in genetic association studies, and its expression could be significantly induced by allergen in airway epithelial cells of mice." (PMID 23577138, 2013). "In addition, we genotyped four SNPs that have been reported to be associated with asthma, rs7216389 in ORMDL3, rs11684634 in PDE11A, rs1544791 in PDE4D and rs2706347 in RAD50." (PMID 23046476, 2012). "To validate whether ORMDL3 is a risk factor for adult-onset asthma, we sought to replicate the association of polymorphisms in ORMDL3, GSDMB, ZPBP2 and IKZF3 and asthma in an adult Chinese Han population." (PMID 21985515, 2011). "This regulation of gene expression by SNPs in this region may be related to some form of systemic immunological function, as variants in this region were also shown to be associated with expression of ORMDL3 in childhood asthma." (PMID 21738480, 2011).
asthma (continued). "In addition, rs2872507, which maps to a locus associated with asthma and influences the expression of the ORMDL3 gene in lymphoblastoid cells, showed a significant association with AS (p = 0.03)." (PMID 21072187, 2010). "The authors also measured global gene expression in Epstein-Barr virus-transformed lymphoblastoid cells from children in their genotyped family samples and found that the markers which showed strongest association with asthma were also consistently associated with transcript levels of ORMDL3." (PMID 18197984, 2008). "Additionally, histone hyperacetylation of the ORMDL3 gene, which is involved in airway remodeling, has been directly associated with asthma development and with the structural changes observed in the airways of asthma patients." (PMID 40806756, 2025). "Notably, the Sphingolipid Biosynthesis Regulator 3 (ORMDL3) gene on chromosome 17 has been implicated in childhood-onset asthma, while the Human Leukocyte Antigen DQ (HLA-DQ) gene has been associated with later-onset asthma." (PMID 39112964, 2024). "Moreover, asthma susceptibility gene ORMDL3 promotes autophagy of human bronchial epithelium." (PMID 37064151, 2023). "However, not much is still known about the role of ORMDLs, particularly ORMDL3 that has been implicated in asthma pathogenesis, in regulating sphingolipid metabolism and levels of bioactive sphingolipid metabolites, and which specific sphingolipid levels are altered." (PMID 33939982, 2021). "FTY720 has been clinically used in patients with multiple sclerosis; thus, our data suggest that it may also be used to treat patients with increased inflammation associated with high ORMDL3 expression in terms of risk alleles for diseases such as asthma and AR." (PMID 34288557, 2021). "Additionally, we demonstrated that ORMDL3 selectively regulates the ATF6 UPR-autophagy signaling pathway, which is an important mechanism to link ORMDL3 to mast cell physiology providing a cellular and molecular explanation for the association between ORMDL3 and asthma pathogenesis." (PMID 33679742, 2021). "Our previous research demonstrated that GBFXD could modulate the microbiota-acetate-regulatory T cell (Treg) axis, downregulate the asthma susceptibility gene ORMDL3, and suppress endoplasmic reticulum (ER) stress responses in a murine model of chronic remission asthma (CRA)." (PMID 34194321, 2021). "Additionally, ORMDL3 (orosomucoid-like 3) has been linked to asthma in several populations, and its corresponding protein may be involved in cell adhesion and integrity; when increased, it has been shown to promote airway remodeling and hyperresponsiveness." (PMID 33255348, 2020). "Hence, one could hypothesize that patients with 17q12-21 asthma risk SNPs correlating with ORMDL3 overexpression may display increased Th2 CD4+ T-cells and associated cytokine profiles." (PMID 33424845, 2020). "Importantly, peripheral blood mononuclear cells (PBMCs) from patients homozygous for the asthma risk SNPs showed increased ORMDL3 mRNA expression and significantly elevated IL-4 and IL-13 production in response to mitogenic and allergen stimuli ex vivo, compared to non-risk SNP carriers." (PMID 33424845, 2020). "However, deletion of ORMDL3 was also associated with increased airway hyperresponsiveness and remodeling, indicating that its mechanistic link to asthma risk is yet unknown." (PMID 33255348, 2020). "Interestingly, the ORMDL3 gene has been associated with severe asthma." (PMID 29966020, 2018). "In addition, variants at the 17q21 asthma locus (ORMDL3) have been specifically associated with asthma in children who had had RV wheezing illnesses early in life, connecting genetic susceptibility, RV infection, and asthma development." (PMID 28620467, 2017).
asthma (continued). "Though the underlying mechanisms functionally linking ORMDL3 to asthma remain largely unknown, a growing body of evidence supports ORMDL3 as contributing to the etiology of asthma, where it likely participates in multiple pathways important to its underlying pathogenesis." (PMID 26637347, 2015). "This proposed connection highlighted the importance of comprehensive in vivo analysis and exploration of the effect of ORMDL3 on asthma immunopathology." (PMID 41939571, 2026). "Eligible studies included pediatric populations with asthma or wheeze phenotypes assessing predefined genetic (ORMDL3, GSDMB) or epigenetic (AHRR, FOXP3, CpG loci) markers and reporting odds ratios (ORs) or sufficient data for their derivation." (PMID 41682911, 2026). "Increased expression of ORMDL3 has been observed in over one-third of children under the age of 7 with asthma." (PMID 41008562, 2025). "Studies show that carriers of the asthma-associated risk allele at 17q21 exhibit increased expression of the corresponding SNP, especially in genes such as GSDMB and ORMDL3." (PMID 40867500, 2025). "However, ORMDL3 is associated with diseases such as asthma, which suggests that the application of vitamin A may have potential risks, and its advantages and disadvantages in the treatment of asthma need to be further studied." (PMID 40672537, 2025). "Among the various epigenetic mechanisms, DNA methylation modifications are the most robustly supported by pediatric studies, particularly those implicating ORMDL3 and GSDMB in asthma susceptibility and inflammation." (PMID 40806756, 2025). "Ceramide/S1P imbalances potentially associated with ORMDL3 and SGMS1 gene polymorphisms have been observed in patients with uncontrolled asthma." (PMID 40559469, 2025). "rs4795405 appears to influence the expression of the major asthma candidate gene ORMDL3, thereby regulating sphingolipid metabolism and endoplasmic reticulum stress responses, which in turn modulate Th2-mediated inflammation and affect asthma severity." (PMID 40110046, 2025). "The study used causal inference in predictive models to screen the indicators with the highest association with asthma disease, including plasma Oromucoid 1-like 3 (ORMDL3), which has a significant correlation with asthma disease in terms of gene expression." (PMID 40161025, 2025). "These in vitro findings prompted in vivo investigation using a murine asthma preparation, where female mice displayed elevated ORMDL3, sphingosine, and S1P levels, with increased airway hyperresponsiveness and remodeling." (PMID 41360340, 2025). "The involvement of GSDMB/ORMDL3 in type 2–low asthma is further illustrated by the effect of ORMDL3 on sphingolipid dysregulation." (PMID 40687950, 2025). "A murine preparation of asthma was used to evaluate sex-dependent differences in ORMDL3 expression, airway responsiveness, and remodeling." (PMID 41360340, 2025). "These coordinated actions contribute to the upregulation of ORMDL3, thereby promoting airway inflammation and remodeling characteristics of asthma." (PMID 41008562, 2025). "The gene cluster comprising ORMDL3 and gasdermin B (GSDMB) is located on chromosome 17q21 and is strongly associated with asthma." (PMID 38562155, 2024). "These same four SNPs in 17q12-21.1 were also in high-LD with two SNPs in ZPBP2 and ORMDL3 (rs12936231 and rs4065275, respectively) that were previously shown to be functionally relevant to asthma." (PMID 38567749, 2024). "Genetic factors related to ER stress, such as orosomucoid-like 3 (ORMDL3), contribute to asthma development by influencing calcium homeostasis, ER stress response, and inflammatory processes." (PMID 39744015, 2024). "GSDMB/ORMDL3 has previously been associated with ICS response and exacerbations for common variants, asthma for common variants, and asthma for the combined effect of rare and common variants." (PMID 38674355, 2024).
asthma (continued). "Elevated protein levels of ORMDL3 were also observed in mice models exhibiting both asthma and obesity." (PMID 38562155, 2024). "Two SNPs in ZPBP2 and ORMDL3 (rs12936231 and rs4065275, respectively) that were previously shown to be functionally relevant to asthma, were also in high-LD with the four SNPs that we identified in the VDR-binding regions of the 17q12-21.1 loci." (PMID 38567749, 2024). "Mutations in these genes, including ORMDL3, GSDMB, ZPBP2, and IKZF3, result in reduced protein folding in the endoplasmic reticulum leading to an overall pro-inflammatory effect in asthma patients." (PMID 39237910, 2024). "ORMDL3 is highly expressed in murine airway epithelial cells and murine models of asthma showed that its expression is further induced following an allergen challenge." (PMID 38715613, 2024). "GWAS studies have strongly linked multiple genetic variants on the regulatory locus of ORMDL3 harboring 17q21 to be associated with diseases such as IBD, diabetes, and asthma." (PMID 38417794, 2024). "Among the protein-coding genes causally associated with unspecified asthma in lung and blood, seven are within the 17q12-21 locus (i.e., PGAP3, IKZF3, GSDMB, ORMDL3, GSDMA, MED24, and CASC3)." (PMID 39628479, 2024). "Functional gastrointestinal disorders (FGID) studies have shown that genes related to asthma, such as DENND1B, SMAD3, SLC22A4/5 (5q31/IBD5), and ORMDL3, have been co-associated with Crohn's disease and ulcerative colitis." (PMID 37656879, 2023). "Given the importance of epithelial integrity in asthma, we assume that ORMDL3 and PGAP3 directly affect the function of renal epithelial cells." (PMID 37064151, 2023). "IBD and asthma also share susceptibility genes, including gene loci DENND1B, SMAD3, SLC22A4/5 (5q31/IBD5) and ORMDL3 gene variants." (PMID 37835065, 2023). "Asthma risk alleles in GSDMA, GSDMB, IKZF3, ZPBP2, and ORMDL3 genes were associated with wheezing illnesses in early childhood, especially rhinovirus-positive wheezing illnesses." (PMID 36967681, 2023). "In the STEPS study, asthma risk alleles in IKZF3, GSDMA, GSDMB, ZPBP2, and ORMDL3 genes were associated with a higher risk of a wheezing illness (all P values ≤.02)." (PMID 36967681, 2023). "Commonly downregulated to PTSD and severe asthma were ORMDL3 (2.2E-2, 1.9E-3, 2.7E-3, 3.9E-3), PTP4A3 (2.6E-3, 2.3E-2, 4.5E-3, 5.2E-3), SHISA4 (1.1E-2, 4.4E-2, 9.8E-3, 6.2E-3), and TPPP3 (2.2E-2, 1.1E-2, 3.1E-3, 2.7E-2)." (PMID 36206293, 2022). "Even more, Alt a 1-asthmatic mice showed an increase of ORMDL-3 and caspase-1 in the asthmatic mice, both markers related to severe asthma." (PMID 35844541, 2022). "ORMDL3 polymorphisms found on chromosome 17q21 have been shown to promote asthma, and when overexpressed, ORMDL3 increases Th2 cytokine production, and subsequently increases childhood asthma susceptibility." (PMID 36292755, 2022). "ORMDL3, an ER-resident transmembrane protein, regulates the activity of serine palmitoyltransferase (SPT), a rate-limiting enzyme in the biosynthesis of sphingolipids, ER stress, and unfolded protein response (UPR), implying the role of ORMDL3 in asthma." (PMID 36430378, 2022). "For example, ORMDL3 located at chromosome 17q21—a major regulator of sphingolipid metabolism—plays an important role in asthma development." (PMID 36818476, 2022). "The locus 17q12-21 encodes several genes including ORMDL3, GSDMB, ZBPB2, and IKZF2, which in fact were linked to asthma in subsequent GWAS and eQTL analyses, and it is one of the most replicated asthma loci to date." (PMID 35055381, 2022). "Another large-scale GWAS for asthma has identified six asthma-susceptible loci, including IL1RL1/IL18R1, SMAD3, ORMDL3/GSDM, IL-33, IL2RB, and HLA-DQ." (PMID 34946955, 2021). "As an ER localized protein, the role of ORMDL3 in the regulation of ERS-induced UPR is an important mechanism to link ORMDL3 to asthma pathogenesis." (PMID 33679742, 2021).
asthma (continued). "GSDMA, GSDMB, and ORMDL3 are statistically independent genetic effects from all shared TWAS genes between asthma and HF." (PMID 35126453, 2021). "Considering that ORMDL3 is highly expressed in patients with asthma and AR, ORMDL3 is thought to regulate inflammatory cytokine expression positively." (PMID 34288557, 2021). "The accumulated analysis supports the potential mechanism, suggesting regulatory SNPs → ORMDL3 → Sphingolipid de novo biosynthesis → airway remodeling in asthma." (PMID 34970542, 2021). "Ceramide synthesis also seems to be involved in asthma, based on the increased expression of Orosomucoid-like 3 (ORMDL3), an endoplasmic reticulum (ER)-resident transmembrane protein that regulates the activity of serine palmitoyltransferase (SPT)." (PMID 35386967, 2021). "In particular, several GWAS for asthma have reported the involvement of the IL-33–IL-1RL1 receptor pathway, with CDHR3 and ORMDL3 being the loci associated with induced eosinophilia and Th2 inflammatory or viral responses." (PMID 34946955, 2021). "SNPs in17q21 showing highly significant associations with childhood asthma correlated with the expression of ORMDL3 transcripts, suggesting ORMDL3 was a plausible asthma candidate gene in the locus." (PMID 33628342, 2021). "ORMDL3-deficient mice are protected in a murine model of asthma with reduced AHR, lung eosinophils, allergen-specific serum IgE, and IL-6 in response to the fungus, Alternaria alternata, while overexpression of ORMDL3 enhanced AHR in this model." (PMID 34122136, 2021). "At present it is not known which of these or other cells alone or in combination express the key ORMDL3-regulated pathways important to the development of asthma." (PMID 33661765, 2021). "Nevertheless, in childhood asthma, although the contribution of both CpG and SNPs in the ORMDL3 expression in whole blood was observed, SNP-CpG interaction did not cooperate in this regulation." (PMID 33781317, 2021). "To date, a number of studies have been performed to investigate the molecular mechanisms by which ORMDL3 contributes to the pathogenesis of asthma." (PMID 33679742, 2021). "Hypermethylation of ORMDL3 from endobronchial airway epithelial cells at the genetic locus 17q12-21 results in asthma in adults." (PMID 34566492, 2021). "We identified three genes (GSDMA in chr17, GSDMB in chr17, and ORMDL3 in chr17) with statistically independent genetic effects from all of the shared TWAS genes between asthma and HF." (PMID 35126453, 2021). "Recent studies employing conditional knockouts of ORMDL3 in airway epithelium have yielded mixed results in murine asthma models, demanding further investigation of ORMDL3 in additional tissues." (PMID 33424845, 2020). "ORMDL3 and GSDMB are promising candidates in this regard because expression levels of these genes are highly correlated with asthma risk genotypes at 17q in blood cells and are also induced by HRV infection." (PMID 32887352, 2020). "Using publicly available mouse developmental gene expression data (GSE21052) we also confirmed the correlation of miR-15a miR-15b with the asthma susceptibility chromosome 17q locus including GSDMA (R = −0.56923) and ORMDL3 (R = +0.6044)." (PMID 33291534, 2020). "The already presented SNP rs12936231 has been reported as a high-risk allele for asthma and autoimmune diseases and suggested to cause chromatin remodeling and alter transcription of certain genes, including ZPBP2, GSDMB, and ORMDL3." (PMID 31362752, 2019). "Current research into ORMDL3 is focused on asthma and autoimmune diseases, so the functional study of its role in cancer is still blank." (PMID 30621577, 2019). "The study identified 99 genetic susceptibility loci, including 136 independent signals implicating genes involved predominantly in immune function, with only six signals showing some disease specificity—eg, ORMDL3 specific for asthma." (PMID 30552067, 2019).